FGF2 (fibroblast growth factor 2)
Diseases named in the same sentence as FGF2 in open-access papers (continued):
Sharing a sentence is not in itself a finding about the gene and the disease.
tumor (continued). "Considering data highlighting the role of FGF-2 in the progression of many cancer types, blocking of FGF-2 may have beneficial effects as shown in reports on the elimination of tumor angiogenesis." (PMID 37443814, 2023). "Indeed, in multiple in vitro and in vivo assays, VEGF-B inhibited FGF2-driven angiogenesis and tumor growth." (PMID 37591843, 2023). "However, a recent study discovered that IFN- produced by T cells in HPD patients stimulates enhanced tumor FGF2 signaling, which ultimately reprograms tumor stem cells and leads to HPD via a sequence of signaling events." (PMID 36831655, 2023). "Additionally, it is known that FGF2-induced tumor angiogenesis is primarily mediated by αvβ3 and α5β1 integrins." (PMID 37569595, 2023). "In the tumor microenvironment, the GSCs can secret cytokines such as fibroblast growth factor 2 (FGF2), hypoxia-inducing factor (HIF), and vascular endothelial growth factor (VEGF) to promote tumor invasion, recruit immune cells, induce angiogenesis, and self-renew." (PMID 36762114, 2023). "Consistent with our hypothesis, the Aspiletreins bound to the targets with high affinity and likely inhibited the tumor-promoting functions of STAT3, VEGFA, HSP90AA1, and FGF2 or enhanced tumor-suppressing activity of IL2, or both." (PMID 36707691, 2023). "FGF2 plays an important role in tumor growth, and targeting FGF2 inhibits tumor angiogenesis." (PMID 37057280, 2023). "CAFs produce angiogenesis regulators, such as VEGFA, PDGFC, FGF2, CXCL12, osteopontin, and CSF3 to promote the growth of tumor-associated blood vessels by recruiting myeloid cells and accelerate tumor angiogenesis by attracting vascular endothelial cells and recruiting monocytes." (PMID 37784082, 2023). "And FGF2 is a member of the fibroblast growth factor (FGF) family and has been implicated in diverse biological processes, such as limb and nervous system development, wound healing, and tumor growth." (PMID 36803385, 2023). "Interestingly, and as occurred with the healthy tissue-derived organoids, those tumor organoids cultured in the presence of FGF2 exhibited a prominent branching morphology, either treated or not with miR-203." (PMID 37542268, 2023). "Fibroblast growth factor 2 (FGF2) could promote tumor angiogenesis, migration, invasion, inflammatory response and stem cell formation in a variety of solid tumors." (PMID 36890467, 2023). "Indeed, IHC analyses of FGF2 on 7 primary patient tumours and corresponding PDXs and PDXOs revealed high FGF2 expression, independent of their FGFR2c status." (PMID 38062117, 2023). "Interestingly, an antiangiogenic action of resveratrol (reduction of VEGF and FGF-2) was suggested to be involved in the tumor reduction of the s.c. xenotransplated human T24 bladder cancer model." (PMID 36901993, 2023). "In addition, studies have shown that fibroblast growth factor-2 (FGF-2) regulates tumor angiogenesis." (PMID 35634419, 2022). "Tumor cell–derived FGFBP1 induces FAPα expression in HSCs via the FGF2/FGFR1/ERK1/-2/EGR1 axis." (PMID 35951441, 2022). "“Angiogenic switch” activators are the tumor microenvironment; mutation in oncogenes or tumor-suppressor genes; pro-angiogenic molecules (VEGF, FGF-2, EGF, PDGF, PIGF, and MMPs); and anti-angiogenic factors (thrombospondin, angiostatin, tumstatin, and endostatin)." (PMID 35454076, 2022). "Similarly, the NG2– cell population, including tumor cells, produced negligible levels of Cxcl14 in both FGF-2+ and FGF-2– tumors." (PMID 35439170, 2022). "We then tested FGF-2 protein levels in various human tumor cell lines." (PMID 35439170, 2022). "By targeting the 3ʹ-UTR region of FGF2,miR-877-3p could act as a suppressor on the proliferation of OS cell lines and exert antiangiogenesis effect on the tumor microenvironment of OS." (PMID 34738872, 2022). "In GBM, FGF2 enhances tumor growth, angiogenesis, and cancer stem cell renewal." (PMID 36046049, 2022).
tumor (continued). "Notably, due to the lack of spontaneous mouse NPC models or mouse NPC cell lines, we exploited other types of mouse tumor for FGF-2 overexpression experiments and genetically modified mouse model experiments." (PMID 35439170, 2022). "VEGF, FGF-2 and HGF can recruit and activate tumour-associated macrophages." (PMID 36362718, 2022). "In addition, tumor cell–derived FGF2 activates a profibrotic phenotype in HSCs, which stimulates ECM synthesis." (PMID 35951441, 2022). "Notably, AGR2 can directly bind to VEGF and fibroblast growth factor 2 (FGF2), thus leading to enhanced metastasis and tumor progression." (PMID 35055132, 2022). "Hence, the accumulation of MCs leads to an increase in neovascularization, mast cell VEGF and FGF-2 expression, tumor aggressiveness, and poor prognosis." (PMID 36419156, 2022). "Since fibroblasts and pericytes distinctively express receptors of FGF-2 in the TME, we hypothesized that FGF-2–promoted tumor metastasis requires assistance from fibroblasts or pericytes." (PMID 35439170, 2022). "In addition, Nguyen’s study showed that high expression of FGF2 in the serum of patients with tumor metastasis is correlated with its clinical status, the extent of disease, and mortality risk." (PMID 36111743, 2022). "Moreover, vascular endothelial growth factor (VEGF) and fibroblast growth factor 2 (FGF2) are believed to be two key angiogenic factors secreted by MSCs that promote tumor neovascularization." (PMID 35269887, 2022). "Taken together, our findings indicated that miR-877-3p might exhibit tumor suppressive role by targeting FGF2 signaling, which may serve as potential target for OS." (PMID 34738872, 2022). "It regulates tumor cell proliferation by binding to fibroblast growth factor 2 (FGF-2)." (PMID 36558015, 2022). "Thus, NPC cells, or FGF-2–expressing malignant cells, orchestrate these 2 cellular components in the tumor stroma to promote metastasis." (PMID 35439170, 2022). "In addition to its role in development, FGF2 also plays key roles under pathophysiological conditions with both cancer cells and cells from their microenvironment producing vast amounts of FGF2 to trigger tumor-induced angiogenesis." (PMID 35433697, 2022). "In addition to VEGF, FGF-2 directly affects ECs through FGF receptors (FGFRs) to stimulate tumor neovascularization and vascular remodeling." (PMID 35985991, 2022). "Interestingly, FGF-2–expressing tumor–bearing mice showed markedly higher CTCs, tumor clones in blood culture, and pulmonary metastasis, compared with that in vector-transfected controls." (PMID 35439170, 2022). "When assessing individual biomarkers that were reported to have a statistically significant association to outcomes and provided hazard ratios, the strongest positive predictors of local and locoregional tumor relapse was FGF2 (LRC, HR = 7.33, p < 0.001), detected in a retrospective study." (PMID 36552043, 2022). "Knockdown of FGF2 markedly reduced NPC tumor growth following implantation in nude mice." (PMID 35985991, 2022). "Here, we demonstrated that bevacizumab treatment induced tumor hypoxia to upregulate the expression of FGFBP1 in tumor cells, which activated the FGF2/FGFR1 signaling pathway to promote HSCs’ transformation into multiple phenotypes, including an “immunogenic” phenotype." (PMID 35951441, 2022). "In addition, under pathophysiological conditions, FGF2 has a strong impact on tumor-induced angiogenesis triggering the formation of new blood vessels to provide the large demands of malignant cancers for nutrients and oxygen." (PMID 35348113, 2022). "In addition, FGF2 knockdown markedly suppressed circulating tumor cells (CTCs), tumor clones in blood culture, and pulmonary metastasis." (PMID 35439170, 2022). "FGF2 secreted by cancer cells regulates proliferation and motility of cancer cells by an autocrine mechanism and stimulates angiogenesis of endothelial cells by a paracrine mechanism, contributing to tumor progression." (PMID 34839358, 2021).
tumor (continued). "Accordingly, the pattern recognition receptor Long Pentraxin 3 (PTX3), a secreted/stromal component of innate immunity able to bind and inactivate various members of the FGF family, including FGF2, has revealed potent anti-angiogenic and anti-tumor properties in different FGF-dependent tumors." (PMID 34066669, 2021). "Neutralizing FGF2 and FGFRs inhibit neovascularization and tumour growth in vivo models." (PMID 33655556, 2021). "Besides its role in physiological angiogenesis, FGF2 is implied in tumor-induced angiogenesis and metastatic process and appears to direct tumor-associated macrophages toward a pro-tumorigenic state." (PMID 33935975, 2021). "Nevertheless, we analyzed the expression of two genes crucial for angiogenesis, namely fibroblast growth factor 2 (Fgf2) and vascular endothelial growth factor A (Vegfa) in tumor samples collected at the end of the experiment, i.e., 26 days after tumor implementation." (PMID 33653008, 2021). "The results revealed that the recombinant ds-Diabody against FGF-2 may be a promising anti-tumor drug for cancer therapy." (PMID 33718141, 2021). "FGF2 is a tumor cell survival factor that helps cells to escape apoptosis." (PMID 34201896, 2021). "Exosomal miR-503 modifies the tumor microenvironment and blocks the angiogenetic process by simultaneously perturbing the expression of two potent pro-angiogenetic molecules, fibroblast growth factor 2 (FGF2) and VEGFA." (PMID 33917233, 2021). "FGF-2 is a potent cell survival factor involved in tumor angiogenesis." (PMID 33572239, 2021). "Furthermore, xenograft tumor model assays showed that the ds-Diabody against FGF-2 had potent antitumor activity in nude mice by inhibiting tumor growth and angiogenesis." (PMID 33718141, 2021). "Moreover, Fib can promote tumour proliferation and stimulate angiogenesis through interactions with fibroblast growth factor 2 and vascular endothelial growth factor." (PMID 33980202, 2021). "Furthermore, FGF2 synergizes with platelet-derived growth factor (PDGF)-BB in the promotion of tumor angiogenesis and the formation of scaffolds through the recruitment of pericytes and vascular smooth muscle cells." (PMID 33535617, 2021). "Insulin like growth factor-1 (IGF1) and estradiol were used as comparative tumor promoters to FGF2." (PMID 34685650, 2021). "Very recently, it was shown that also FGF2 could be a major modulator in macrophage polarization, at least in tumor development." (PMID 34067330, 2021). "Since HS is required for FGF2 signal activation as a receptor, we hypothesized that the tumor suppressive effect was due to the attenuation of angiogenesis in brain capillaries." (PMID 34790962, 2021). "The ds-Diabody against FGF-2 might possess significant effect on tumor therapy, compared to Avastin, and could be considered as a potential candidate for cancer therapy." (PMID 33718141, 2021). "As CD 138 interacts with heparin binding growth factors such as fibroblast growth factor-2, its accumulation in tumor stroma might contribute to angiogenesis, cell proliferation and migration, tumor pathogenesis and cell–matrix interactions." (PMID 34952631, 2021). "For instance, it has been suggested that FGF2 may act as an important tumor-promoting factor, in accordance with data showing that its levels are elevated in TNBC cells and in plasma samples of TNBC and other types of tumors." (PMID 33946884, 2021). "Functional blood vessels must undergo endothelial cell proliferation initiated by Vascular Endothelial Growth Factor (VEGF) and basic Fibroblast Growth Factor (FGF-2; bFGF) which are primary mediators of blood vessels, significantly upregulated in the vicinity of a tumor." (PMID 34445691, 2021). "Additionally, in vitro studies reported that tumour cells can produce endogenous fibrinogen and the combination of FGF-2 and fibrinogen can stimulate the proliferation of endothelial cells, leading to enhanced angiogenesis." (PMID 34056114, 2021).
tumor (continued). "It is frequently detected in tumors and contributes to the formation of tumor-reactive stroma; moreover, fibrogen can promote tumor angiogenesis by binding several growth factors including fibroblast growth factor 2 (FGF-2) and vascular endothelial growth factor (VEGF), leading to tumor progression." (PMID 34284775, 2021). "Therefore, a higher expression of FGFR2c resulted in a more pronounced responsiveness of tumor cells to FGF2 in terms of intracellular signaling activation." (PMID 34638477, 2021). "Together with the loss of FGF2 expression, activation of the TGFβ/AKT axis could lead to Postn induction in tumor cells, contributing to increased invasion and worse outcomes." (PMID 34809697, 2021). "Inhibiting FGF2-FGFR signaling in mice indeed improved tumor sensitivity to anti-VEGF therapy, suggesting that therapeutic strategies that target both growth factors could form a stronger anti-angiogenic intervention in cancer." (PMID 33614496, 2020). "In addition, mast cells chemotactically respond to VEGF-A and FGF2, indicating that a connection between mast cell accumulation at tumor sites, angiogenesis and tumor growth exists." (PMID 33343570, 2020). "As we had verified that HOXD-AS1 was a metastasis promoter by accelerating migration and invasion of CC cells, we then sought to determine whether this tumor promoting activity of HOXD-AS1 was mediated by the miR-877-3p/FGF2 axis." (PMID 32977766, 2020). "Likewise, the opposing or cooperative effects of FGF2 and anosmin-1 on tumor cells are still to be evaluated." (PMID 32498223, 2020). "Thus similar to the results with tumours in Fgf2LMW−/− mice, the addition of anti-FGF2 blocking antibody delayed growth of irradiated MC38 tumours." (PMID 32792542, 2020). "Additionally, the expression levels of FGF-2 and PDGFβ in E10 as well as G11 tumor tissues were decreased." (PMID 32983976, 2020). "In addition, alternative pro-angiogenic signaling pathways including ANGPT-2, FGF-2, IL-8 can be induced by tumor cells in response to a pharmacological inhibition of the VEGF signaling pathway." (PMID 31690961, 2020). "In these tumours TAMs were the predominant immune cells that expressed FGF2 and its receptors." (PMID 32792542, 2020). "Inhibit tumor angiogenesis, via FGF2/FGFR system, proliferation and apoptosis." (PMID 33013829, 2020). "A possible mechanistic explanation of the elevated angiogenic response would attribute ablation of vascular pericytes by PDGFRβ inhibition, allowing further exposure of tumor vessels to FGF-2 and VEGF, and consequently leading to excessive sprouting of microvessels." (PMID 32709869, 2020). "In collaboration with VEGF, fibroblast growth factor 2 (FGF)-2 can promote tumor angiogenesis." (PMID 32422991, 2020). "While the results in tissue culture not surprisingly do not fully replicate the expression patterns in vivo, these experiments suggest that FGF2 alters the phenotypes of TAMs, and may be critical in allowing macrophages to generate a pro-tumour response." (PMID 32792542, 2020). "HLFs are stromal cells that support vascular sprouting and tumor invasion by secreting growth factors, such as fibroblast growth factor 2 (FGF-2) and vascular endothelial growth factor (VEGF)—both of which promote the formation of healthy blood vessels through angiogenesis." (PMID 33214583, 2020). "It is known that tumor-associated macrophages (TAMs) exhibit similar functions to M2 macrophages and MALAT1 was upregulated in TAMs compared to nonpolarized macrophages and promoted angiogenesis through secretion of fibroblast growth factor-2 (FGF2) protein." (PMID 32190702, 2020). "MC38 FGF2 staining intensity was increased in irradiated tumours compared with unirradiated." (PMID 32792542, 2020). "Tumor-secreted FGF2, in conjunction with VEGF, promotes tumor angiogenesis." (PMID 33614496, 2020). "Similarly, the combination therapy produced a synergistic antitumor activity on FGF-2+ fibrosarmas by inhibiting tumor angiogenesis." (PMID 32709869, 2020).
tumor (continued). "Furthermore, FGF2 levels are increased in the tumour microenvironment following irradiation in vivo." (PMID 32792542, 2020). "FGF-2 has long been known as a potent angiogenic factor that stimulates tumor neovascularization." (PMID 32709869, 2020). "Here, fibroblast growth factor FGF2 and 10, hEGF, IGF and PDGF were used as PDAC shows an overexpression of their receptors, being associated with angiogenesis, desmoplastic reaction and tumor growth." (PMID 32404074, 2020). "Moreover, FGF-2 leaking out from gefitinib-treated NSLC cells was proposed as a survival factor for tumor cells that remained alive after the first exposure of EGFR-TKIs and further maintained their resistance to EGFR-TKIs." (PMID 32599808, 2020). "In addition to aHSCs and tumor cells, neutrophils from liver metastases were also shown to express pro‐angiogenic factors including fibroblast growth factor 2 (FGF2)." (PMID 33252863, 2020). "Tumor over-expressing the mouse VEGFR2 extracellular domain fused with the human IgG4 fragment crystallizable (Fc) region (VEGFR-2-Fc) showed highest levels of mRNA expression from FGF2 and other factors of FGF-2/FGFR-2 pathway." (PMID 32456056, 2020). "FGF-2 protein expression in tumor tissues was examined by IHC." (PMID 33746736, 2020). "The release of these angiogenic factors (VEGF-A, HGF, SDF1, PlGF, FGF-2, MCP-3, and IL-8), induced by hypoxia in the tumor tissue may be associated with anti-VEGF resistance." (PMID 32456056, 2020). "HOXD-AS1 functions as a tumor-promoting lncRNA via the miR-877-3p/FGF2 axis in CC." (PMID 32977766, 2020). "Indeed, increased FGF-2 levels in serum and tumor specimens were found in IM-treated mice bearing IM-resistant GIST xenografts, whereas BGJ398 used in combination with IM effectively inhibited their growth." (PMID 32599808, 2020). "We found that FGF2-SPIONs treatment alone inhibited the tumor stroma-induced spheroid growth." (PMID 31911892, 2020). "By treating the patient with anti-VEGF agents, the VEGF-dependent vessels will be targeted and disrupted, whilst the tumor vessels will be increasingly covered by pericytes; these pericytes have been shown to overexpress FGF2, thereby switching the angiogenic pathway dependency towards FGF2." (PMID 33121202, 2020). "FGF2 plays an important role in tumor progression and malignancy." (PMID 33381388, 2020). "In addition to VEGF, fibroblast growth factor 2 (FGF-2) and platelet-derived growth factors (PDGFs) significantly contribute to tumor neovascularization and vascular remodeling." (PMID 32709869, 2020). "Following secretion from tumor cells and their cellular microenvironment, FGF2 exerts its biological functions through both autocrine and paracrine signaling mediated by the formation of ternary complexes with FGF high-affinity receptors and heparan sulfates on cell surfaces." (PMID 32214225, 2020). "We asked whether an anti-FGF2 blocking antibody would similarly affect the tumour response to radiotherapy." (PMID 32792542, 2020). "Similarly, increased FGF-2 expression in tumor specimens from IM-treated patients revealed the activation of FGF2-signaling in GISTs in vivo." (PMID 32599808, 2020). "Furthermore, FGFR2-Fc significantly suppressed FGF2-induced tube formation in a HUVEC sandwich tube formation assay in which HUVECs were co-cultured with FGFR2-Fc–expressing tumor cells." (PMID 32076044, 2020). "Consequently, the combination-treated FGF-2+ tumors experienced a high degree of hypoxia, marked repression of tumor cell proliferation, and significantly increased apoptosis." (PMID 32709869, 2020). "Furthermore, in stroma-rich 3D heterospheroids, we demonstrated that FGF2-SPION were highly effective in reducing stroma-induced tumor spheroid growth." (PMID 31911892, 2020). "Interestingly, expression of FGF-2 in this cell line markedly accelerated the in vivo tumor growth rate." (PMID 32709869, 2020).